HOXB9 (homeobox B9)
Diseases named in the same sentence as HOXB9 in open-access papers (continued):
Sharing a sentence is not in itself a finding about the gene and the disease.
cancer (continued). "The expression of HOXB9 was significantly upregulated in pan-cancer, including EC (P < 0.05)." (PMID 36803556, 2023). "The results suggested that HOXB9 was increased in most cancer types." (PMID 37301547, 2023). "Based on these findings, HOXB9 holds great promise as a reliable immunotherapy biomarker for cancer and may have significant clinical implications for cancer treatment." (PMID 37301547, 2023). "HOXB9 may act as a new predictor to assess cancer prognosis and therapeutic efficacy of the immune in various cancers." (PMID 37301547, 2023). "In addition, HOXB9 was upregulated in the lymph nodes at all stages of cancer development, and in the high-grade tumors compared to normal tissues." (PMID 37657018, 2023). "Further, we explored the prognostic value of HOXB9 for pan-cancer." (PMID 37301547, 2023). "HOXB9 is a HOX gene involved in the regulation of several human cancers." (PMID 37964257, 2023). "Moreover, the cancer type with the highest frequency of HOXB9 alterations was UCS, exceeding 6% of UCS patients, and amplification." (PMID 37301547, 2023). "Additionally, up-regulation of HOXB9 results in poor overall survival in many cancer patients and promotes epithelial–mesenchymal transformation." (PMID 36803556, 2023). "In this article, we explored the expression levels and prognosis of HOXB9 in pan-cancer." (PMID 37301547, 2023). "Thus, this study represents the first attempt to comprehensively elucidate the tumorigenic role of HOXB9 across various types of cancer, and it offers valuable insights that can guide future research on HOXB9." (PMID 37301547, 2023). "We used TISCH at the single-cell level to analyze the pan-cancer expression pattern of HOXB9." (PMID 37301547, 2023). "HOXB9 and CSC markers were simultaneously overexpressed in human refractory PCa tissues, compared with low-grade PCa, para-carcinoma, and initial PCa tissues implying the involvement of HOXB9 signalling’s involvement in ALDH+CD44+CXCR4+CD24+-PCa cell-rendered castration resistance." (PMID 34247196, 2021). "Further study is required to re-evaluate the role of HOXB9 in cancer." (PMID 32104178, 2020). "HOXB9 has been reported to promote tumorigenesis in various types of cancers; however, no previous research on HOXB9 has shown a mRNA variant of HOXB9." (PMID 32104178, 2020). "Therefore, the function of HOXB9 deserves further scrutiny as it appears to be dependent on cancer type and/or stage." (PMID 33411683, 2020). "Interestingly, bioinformatics analysis of TCGA cancer database showed that HOXB9 expression is positively correlated with E2F3 expression." (PMID 29724991, 2018). "For instance, a hypomethylation was observed in CpG sites associated with cancer-related genes: leucine-rich repeat-containing 26 (LRRC26), homeobox B9 (HOXB9), and BR serine/threonine kinase 2 (BRSK2) only in boys, which correlated with an increase in As levels." (PMID 30873799, 2018). "The discrepancy in the basal expression level and normal function of HOXB9 in these tissues may reflect the opposite roles of HOXB9 in various cancers." (PMID 26536658, 2015). "Both of HOXB9-induced cancer cells showed accelerated tumorigenesis." (PMID 24885802, 2014). "HOXB9 significantly enhanced angiogenesis, and bevacizumab administration significantly reduced angiogenesis of HUVECs co-cultured with HOXB9-overexpressing cancer cells." (PMID 24885802, 2014). "Furthermore, based on the CCLE data, we observed the HOXB9 expression in various cancer cell lines." (PMID 37301547, 2023). "This hypothesis is supported by findings from studies conducted in other types of cancer, showing that HOXB9 knockdown results in cell-cycle arrest, indicating that it may be an important molecular component of the cell cycle and may be a promising target for novel personalised gene therapy." (PMID 35216396, 2022).
cancer (continued). "Interestingly, HOXB9 has recently been recognised as an important TF that plays a vital role in cancer progression by activating EMT through important signalling pathways, including the transforming growth factor beta (TGF-β) and wingless-related integration site (WNT) signalling pathways." (PMID 35216396, 2022). "They found that HOXB9 acetylation may account for its inhibitory role in cancer cells." (PMID 36158877, 2022). "Thus, we speculate that HOXB9 may activate TGFβ/Smad2 signalling, which in turn alters a panel of downstream target genes involved in cancer cell invasion and metastasis." (PMID 34247196, 2021). "In addition, we performed wound-healing assays to determine whether HOXB9 affects the cancer cell migration." (PMID 29724991, 2018). "Subsequently, HOXB9 interacts with ODC1, preventing its degradation and leading to the accumulation of polyamines, thus promoting cancer progression." (PMID 41402312, 2025). "Our analysis demonstrated a positive correlation between HOXB9 expression and the infiltration levels of CAF, Endo, MDSC, macrophages, dendritic cells, and NK cells in most of the TCGA cancers." (PMID 37301547, 2023). "The HOXB9 expression data of HNSCC and normal tissues were compared using the gene expression profiling interactive analysis (GEPIA) and the cancer genome atlas (TCGA) databases." (PMID 37657018, 2023). "Therefore, the role of HOXB9 in cancers may be more complicated than we assumed." (PMID 36158877, 2022). "At the same time, HOXB9 negatively regulates RTK, thus inhibiting the proliferation of cancer cells." (PMID 34306077, 2021). "HOXB9, as a HOX family transcription factor, playing a significant role in embryonic development and cancer progression." (PMID 29724991, 2018). "We demonstrated that the potent anti-angiogenic effect of miR-192 stems from its ability to globally downregulate angiogenic pathways in cancer cells through regulating two key transcription factors, EGR1 and HOXB9." (PMID 27041221, 2016). "HOXB9 transcript appears to important either in primary OSCCs and OSCC-derived CTCs, as we found the same tendency between the A.C. Camargo Cancer Center cohort and the Ohio State University cases." (PMID 26041877, 2015). "The other HOX genes that are notably upregulated in SK-OV3 cells (but generally not OV-90 cells) have previously been shown to be upregulated in other cancers, including HOXA13, HOXB5, HOXB9 and HOXD9." (PMID 20219106, 2010). "The results showed that some HOX genes in pan-cancer had significant strong correlation (R≥0.8): HOXA9 with HOXA10, HOXB5 with HOXB6 and HOXB8, HOXB8 with HOXB6 and HOXB9, HOXB3 with HOXB4 and HOXB5 and HOXB6, HOXC8 with HOXC9, HOXC9 with HOXC10, HOXD10 with HOXD11." (PMID 39980564, 2025). "HOXB9 is not only a pro-cancer transcription factor but also a central player in lipid and polyamine metabolism, highlighting the non-transcriptional regulatory function of HOXB9." (PMID 41402312, 2025). "HOXB9 mRNA is elevated in multiple cancers, and was upregulated in HNSCC tissues compared to non-paired (P < .05 in GEPIA; P < .0001 in TCGA) as well as paired (P < .0001 in TCGA) normal tissues." (PMID 37657018, 2023). "In addition, the HOXB9-induced upregulated expression of SSP1 and MMP9, two well-known cancer metastasis promoters, was suppressed by TGFβ inhibitor." (PMID 34247196, 2021). "The results showed that HOXB9 was abundant in PCa tissues, but weak or not expressed in para-carcinoma and benign prostate hyperplasic tissues." (PMID 34247196, 2021). "Although not a transforming oncogene, HOXB9 has been shown to promote cancer progression and metastasis in different tumors via induction of cell motility and angiogenesis." (PMID 33171691, 2020). "Although HOXB9 has been extensively investigated in some cancer types, its role in EC has never been reported." (PMID 29724991, 2018).
cancer (continued). "Interestingly, the expression of PD-L1, HOXB9 and ZNF813 were similar to that found in primary tumors from A. C. Camargo Cancer Center, especially in larger tumors." (PMID 26041877, 2015). "We have shown that HOXB9 enhances migration, invasion and proliferation of both HNSCC and OPM cells in keeping with the effects of high HOXB9 expression in other cancers, but which has not been demonstrated previously in HNSCC or in pre-invasive disease." (PMID 25860510, 2015). "In addition, HOXB9 and BRKS2 are worth mentioning as they were among the cancer-related genes and among the top 20 genes for boys." (PMID 24965135, 2014). "Additionally, to investigate whether HOXB9-overexpression was related to cancer progression, we determined the expression level of genes related to EMT, angiogenesis, cancer stemness and apoptosis using RT-PCR." (PMID 36674764, 2023). "In trophoblast cells, HOXB9 could contribute to the implantation process by promoting the epithelial-to-mesenchymal transition (EMT), angiogenesis, cell migration and invasion (mouse) through the regulation of angiogenic factors and TGF-β2, as evidenced in cancers." (PMID 27798681, 2016). "Next, the significant relationship between the expression of HOXB9 and the pathological stages was found in the CESC, HNSC, PAAD, and LIHC (P < 0.05) but not other cancers." (PMID 37301547, 2023).
adenocarcinoma (2 papers, 2014 to 2015). A common cancer characterized by the presence of malignant glandular cells. "HOXB9 mRNA expression was significantly higher in poorly differentiated adenocarcinomas than in highly and moderately differentiated types of adenocarcinomas and was highly related to liver metastasis." (PMID 24885802, 2014).
HOXB9 also shares sentences with these, for which no sentence is quoted: head and neck squamous cell carcinoma (4 papers); atypical endometrial hyperplasia (2); gastric adenocarcinoma (2); acute megakaryoblastic leukemia (1); adrenocortical adenoma (1); bladder cancer (1); bladder urothelial carcinoma (1); breast invasive carcinoma (1); cholangiocarcinoma (1); depression (1); esophageal carcinoma (1); gastric tumors (1); hematological disorders (1); hypercholesterolaemia (1); hyperplasia (1); lung squamous cell carcinoma (1); metabolic disorder (1); metabolic syndrome (1); mouth neoplasms (1); oral cancer (1); ovarian tumor (1); prostate carcinoma (1); rectum adenocarcinoma (1); renal clear cell carcinoma (1); schizophrenia (1); serous ovarian cancer (1); thyroid carcinoma (1).